PPP1CA (protein phosphatase 1 catalytic subunit alpha)
Description:
Protein phosphatase that associates with over 200 regulatory proteins to form highly specific holoenzymes which dephosphorylate hundreds of biological targets. Protein phosphatase 1 (PP1) is essential for cell division, transcription elongation, and participates in the regulation of glycogen metabolism, muscle contractility and protein synthesis. Involved in regulation of ionic conductances and long-term synaptic plasticity. May play an important role in dephosphorylating substrates such as the postsynaptic density-associated Ca(2+)/calmodulin dependent protein kinase II. Catalytic component of the PNUTS-PP1 protein phosphatase complex, a protein phosphatase 1 (PP1) complex that promotes RNA polymerase II transcription pause-release, allowing transcription elongation: the PNUTS-PP1 complex mediates the release of RNA polymerase II from promoter-proximal region of genes by catalyzing dephosphorylation of proteins involved in transcription, such as AFF4, CDK9, MEPCE, INTS12, NCBP1, POLR2M/GDOWN1 and SUPT6H. The PNUTS-PP1 complex also regulates transcription termination by mediating dephosphorylation of SUPT5H in termination zones downstream of poly(A) sites, thereby promoting deceleration of RNA polymerase II transcription. PNUTS-PP1 complex is also involved in the response to replication stress by mediating dephosphorylation of POLR2A at 'Ser-5' of the CTD, promoting RNA polymerase II degradation. PNUTS-PP1 also plays a role in the control of chromatin structure and cell cycle progression during the transition from mitosis into interphase. Regulates NEK2 function in terms of kinase activity and centrosome number and splitting, both in the presence and absence of radiation-induced DNA damage. Regulator of neural tube and optic fissure closure, and enteric neural crest cell (ENCCs) migration during development (By similarity). In balance with CSNK1D and CSNK1E, determines the circadian period length, through the regulation of the speed and rhythmicity of PER1 and PER2 phosphorylation. May dephosphorylate CSNK1D and CSNK1E. Dephosphorylates the 'Ser-418' residue of FOXP3 in regulatory T-cells (Treg) from patients with rheumatoid arthritis, thereby inactivating FOXP3 and rendering Treg cells functionally defective. Dephosphorylates CENPA. Dephosphorylates the 'Ser-139' residue of ATG16L1 causing dissociation of ATG12-ATG5-ATG16L1 complex, thereby inhibiting autophagy. Together with PPP1CC (PP1-gamma subunit), dephosphorylates IFIH1/MDA5 and RIG-I leading to their activation and a functional innate immune response. Core component of the SHOC2-MRAS-PP1c (SMP) holophosphatase complex that regulates the MAPK pathway activation. The SMP complex specifically dephosphorylates the inhibitory phosphorylation at 'Ser-259' of RAF1 kinase, 'Ser-365' of BRAF kinase and 'Ser-214' of ARAF kinase, stimulating their kinase activities. The SMP complex enhances the dephosphorylation activity and substrate specificity of PP1c. (Microbial infection) Necessary for alphaviruses replication.
Synonyms: PP-1A; PPP1A; PP1A; PP1alpha
Tractability: Small molecule: a structure with a bound ligand is known; a high-quality ligand is known; it belongs to a druggable protein family. Antibody: its Gene Ontology location is reachable by antibodies, with high confidence. PROTAC: ubiquitination databases record sites on it; its protein half-life has been measured; a small molecule that binds it is known.
Target class: Protein Phosphatase; Phosphatase; Serine/threonine protein phosphatase; Enzyme
Gene: Protein-coding gene on chromosome 11 (67,398,179 to 67,421,183, reverse strand). Ensembl gene ENSG00000172531.
Subcellular location: Cytoplasm; Nucleus; Nucleus, nucleoplasm; Nucleus, nucleolus; Postsynaptic density
Subcellular location (Human Protein Atlas): Cytosol; Nucleoplasm; Plasma membrane; End piece; Flagellar centriole; Mid piece
Pathways (Reactome):
Signal Transduction: DARPP-32 events; Downregulation of TGF-beta receptor signaling
Circadian clock: Phosphorylation and nuclear translocation of the CRY:PER:kinase complex
Disease: Maturation of hRSV A proteins
Metabolism: Triglyceride catabolism
Metabolism of RNA: mRNA Polyadenylation
Gene Ontology:
Molecular function: cadherin binding involved in cell-cell adhesion; iron ion binding; phosphatase activity; phosphoprotein phosphatase activity; protein binding; protein serine/threonine phosphatase activity; RNA polymerase II CTD heptapeptide repeat S5 phosphatase activity; transition metal ion binding; hydrolase activity; protein phosphatase 1 binding; protein-containing complex binding; ribonucleoprotein complex binding
Biological process: negative regulation of transcription elongation by RNA polymerase II; positive regulation of termination of RNA polymerase II transcription, poly(A)-coupled; positive regulation of transcription elongation by RNA polymerase II; protein dephosphorylation; protein stabilization; regulation of circadian rhythm; RNA polymerase II promoter clearance; telomere maintenance in response to DNA damage; circadian regulation of gene expression; entrainment of circadian clock by photoperiod; positive regulation of Ras protein signal transduction; regulation of canonical Wnt signaling pathway; regulation of translational initiation in response to stress; response to lead ion; cell-cell adhesion; positive regulation of glycogen biosynthetic process; regulation of glycogen biosynthetic process; regulation of glycogen catabolic process
Cellular component: adherens junction; chromosome, telomeric region; cytoplasm; cytosol; endoplasmic reticulum; extracellular exosome; nucleoplasm; nucleus; protein phosphatase type 1 complex; PTW/PP1 phosphatase complex; dendritic spine; glutamatergic synapse; glycogen granule; neuronal cell body; nucleolus; perikaryon; postsynapse; postsynaptic density; presynapse
Genetic constraint (gnomAD): Loss-of-function variants: 14 observed, 39.51 expected, observed/expected ratio (o/e) 0.35, 90% interval 0.23 to 0.55. The upper end of that interval is the gene's LOEUF score, 0.55, which puts it in group 2 of 6, group 1 being the genes least tolerant of losing a copy. Missense variants: 277 observed, 451.77 expected, observed/expected ratio (o/e) 0.61, 90% interval 0.56 to 0.68. Synonymous variants: 200 observed, 182.57 expected, observed/expected ratio (o/e) 1.1, 90% interval 0.98 to 1.23.
Homologues: Orthologues: dog PPP1CA (100% identical), guinea pig PPP1CA (100% identical), pig PPP1CA (100% identical), rat Ppp1ca (100% identical), mouse Ppp1ca (99% identical), macaque PPP1CA (96% identical), chimpanzee PPP1CA (91% identical), Drosophila melanogaster Pp1-87B (85% identical), Drosophila melanogaster Pp1-13C (83% identical), rabbit PPP1CA (76% identical), Caenorhabditis elegans ZK938.1 (51% identical), Caenorhabditis elegans F23B12.1 (49% identical), and 23 more. Paralogues in human: PPP1CC (91% identical), PPP1CB (88% identical), PPP2CB (45% identical), PPP2CA (44% identical), PPP4C (43% identical), PPP6C (42% identical), PPP3CA (40% identical), PPP3CB (39% identical), PPP3CC (39% identical), PPP5C (34% identical), PPEF2 (32% identical), PPEF1 (32% identical).
Diseases named in the same sentence as PPP1CA in open-access papers:
PPP1CA is named in the same sentence as 59 diseases in open-access papers, as found by Europe PMC text mining. Sharing a sentence is not in itself a finding about the gene and the disease. The quoted sentences say what the papers report.
breast carcinoma (10 papers, 2007 to 2025). "In breast cancer, PPP1CA is highly expressed in tumour tissues and associated with poorer overall survival." (PMID 39550701, 2024). "We found that the PPPCs family had high diagnostic accuracy for breast cancer, with PPP1CA, PPP4C and PPEF1 having the highest diagnostic accuracy." (PMID 34964699, 2022). "PRKACG, PRKAR1B and PPP1CA were the most strongly and reproducibly associated with breast cancer–specific survival." (PMID 33991172, 2021). "PPP1CA is a member of the phosphoprotein phosphatase catalytic subunit family involved in human breast cancer development and progression." (PMID 40839607, 2025). "The alterations of PPP1CA, PPP3CA, PPP3CB and PPP6C were significantly associated with the prognosis of breast cancer." (PMID 34964699, 2022). "Among the highly expressed genes in breast cancer tissues, PPP1CA was negatively correlated with CD8 + T cell and macrophage infiltration, while PPP2CA was positively correlated with infiltration." (PMID 34964699, 2022). "The mRNA expression level of PPP1CA in 40 breast cancer patients and the protein expression level of PPP1CA in 60 breast cancer patients were significantly higher in breast cancer tissues than in paracancerous tissues." (PMID 34964699, 2022). "After intervention with siRNA in breast cancer cells, the mRNA expression levels and protein expression levels of PPP1CA or PPP4C in MCF-7 and MD-MB-468 cell lines were significantly decreased." (PMID 34964699, 2022). "Our findings suggest that PPP1CA, PRKACG and PRKAR1B are associated with breast cancer–specific survival." (PMID 33991172, 2021). "PKA and PP1 subunit mRNA was also assessed; PPP1CA, PRKACG and PRKAR1B were associated with breast cancer–specific survival." (PMID 33991172, 2021). "PKA and PP1 subunit mRNA expression was also assessed; PPP1CA, PRKACG and PRKAR1B were associated with breast cancer–specific survival." (PMID 33991172, 2021). "In conclusion, the PPPCs family, especially PPP1CA and PPP4C, could be used as new biomarkers to improve diagnostic accuracy, predict prognosis and novel targets for the treatment of breast cancer." (PMID 34964699, 2022). "Therefore, inhibition of PPP1CA may play an important role in inhibiting breast cancer proliferation and metastasis." (PMID 34964699, 2022). "Among these, ABCC3, ACPP, PPP1CA, PRKAG3, and RNASEL exhibited interactions with several proteins, immune checkpoint markers, and chemotherapeutic drugs administered in both human breast cancer and FMC." (PMID 40839607, 2025). "To verify that PPP1CA and PPP4C indeed promote the development of breast cancer, we conducted in vitro experiments on these genes." (PMID 34964699, 2022). "Although we validated the expression levels of PPP1CA and PPP4C in breast cancer tissues and their effects on the biological behavior of breast cancer cells, further investigation of their molecular mechanisms is needed." (PMID 34964699, 2022). "We demonstrated in vitro that inhibition of PPP1CA and PPP4C expression significantly inhibited breast cancer proliferation and migration." (PMID 34964699, 2022). "We also validated the changes we identified by establishing siRNA knockout models for PPP1CA and PPP4C to investigate the biological impact in breast cancer cell culture." (PMID 34964699, 2022). "We found that ABCC3, ACPP, PPP1CA, PRKAG3, and RNASEL were involved in the tumorigenesis of FMC and exhibited interactions with proteins and chemotherapeutic drugs relevant to both human breast cancer and FMC." (PMID 40839607, 2025). "We therefore concluded that both PPP1CA and PPP4C have a significant effect on the proliferation and metastasis of breast cancer, but whether these genes lead to a worse prognosis in breast cancer needs to be supported by more clinical data." (PMID 34964699, 2022).
breast carcinoma (continued). "Among the PPPCs family, PPP1CA and PPP4C played a prominent role in the progression of breast cancer, and inhibition of PPP1CA and PPP4C expression by siRNA can significantly inhibit breast cancer cells proliferation and migration." (PMID 34964699, 2022). "In the Oncomine database, when compared with normal breast tissues, PPP1CA, PPP2CA, PPP4C and PPEF1 were significantly elevated in breast cancer tissues, while PPP1CB, PPP2CB, PPP3CA, PPP3CB, PPP3CC and PPP6C were significantly decreased in breast cancer tissues." (PMID 34964699, 2022). "We subsequently inhibited the expression of PPP1CA and PPP4C in breast cancer cells by siRNA and observed changes in their proliferation and migration abilities, and verified through these results that these two genes played an outstanding role in the development of breast cancer." (PMID 34964699, 2022).
prostate carcinoma (6 papers, 2007 to 2024). A carcinoma that arises from epithelial cells of the prostate gland. "For instance, PPP1CA dephosphorylates B-Raf at both ERK phosphorylation sites to trigger PPP1CA/B-Raf/ERK pathway activation and promote prostate cancer (CaP) cell invasiveness." (PMID 38360682, 2024).
COVID-19 (5 papers, 2020 to 2024). A disease caused by infection with severe acute respiratory syndrome coronavirus 2. "In the COVID-19 comparison group, five DEPs, PPP1CA, YWHAH, YWHAB, YWHAZ, and TP53BP2, were enriched with the first three upregulated and TP53BP2 downregulated, whereas the PQ group exhibited enrichment only in Smad4 within this pathway." (PMID 39301288, 2024).
hepatocellular carcinoma (5 papers, 2022 to 2025). A malignant tumor that arises from hepatocytes. "In hepatocellular carcinoma, miR‐449a‐5p enhances the anti‐tumour effects of sorafenib by down‐regulating PPP1CA, including inhibiting cell proliferation and angiogenesis and inducing apoptosis." (PMID 39550701, 2024). "Here, we demonstrated that miR-449a-5p strongly potentiates sorafenib-induced apoptosis of hepatocellular carcinoma cells by downregulating PPP1CA in particular." (PMID 34976171, 2022). "To determine the relevance of PEA15, PPP1CA and TUFT1 in hepatocellular carcinoma in vivo, we analyzed three publically available expression datasets of primary HCCs." (PMID 34976171, 2022). "In this study, we comprehensively investigated the impact of miR-449a-5p and its target genes PEA15, PPP1CA and TUFT1 on the effects of sorafenib treatment in hepatocellular carcinoma." (PMID 34976171, 2022). "In the publication at hand, we focus on the characterization of the miR-449a-5p targetome and analyze the impact of miR-449a-5p and its target genes PEA15, PPP1CA and TUFT1 on the efficacy of sorafenib in hepatocellular carcinoma." (PMID 34976171, 2022). "In the following, we focused on PEA15, PPP1CA and TUFT1 because they showed a strong regulation in qRT-PCR and literature research of these genes indicated promising approaches for the treatment of hepatocellular carcinoma." (PMID 34976171, 2022). "Our findings demonstrate that PEA15, PPP1CA and TUFT1 are frequently overexpressed in HCC and that patients with hepatocellular carcinoma may benefit from the repression of these genes." (PMID 34976171, 2022). "Moreover, in hepatocellular carcinoma and osteoblasts, CARM1 induces complex metabolic reprogramming by methylating targets including Malate Dehydrogenase 1 (MDH1), Glyceraldehyde-3-Phosphate Dehydrogenase (GAPDH), and Protein Phosphatase 1 Catalytic Subunit Alpha (PPP1CA)." (PMID 41488004, 2025).
glioblastoma (4 papers, 2020 to 2025). The most malignant astrocytic tumor (WHO grade IV). "In glioblastoma, PPP1CA increases with increasing tumour grade and associated with poorer prognosis." (PMID 39550701, 2024). "On the other hand, KIF18A could promote the malignant development of glioblastoma by binding to PPP1CA." (PMID 38057879, 2023). "In glioblastoma, KIF18A inhibition suppresses cell growth, migration and invasion, and induces G2/M cell-cycle arrest of glioblastoma cells via interacting with PPP1CA." (PMID 40175357, 2025).
colorectal cancer (3 papers, 2022 to 2023). A primary or metastatic malignant neoplasm that affects the colon or rectum. "Interestingly, the findings of another study indicated that USP11 promotes growth and metastasis by stabilizing PPP1CA in colorectal cancer, suggesting that DUBs could have opposite functions via regulating different proteins in diverse diseases." (PMID 37151889, 2023).
glioma (3 papers, 2020 to 2025). A benign or malignant brain and spinal cord tumor that arises from glial cells (astrocytes, oligodendrocytes, ependymal cells). "The CGGA database was used to examine the expression level of PPP1CA in gliomas of various grades online." (PMID 40027130, 2025). "The findings demonstrated a substantial rise in PPP1CA expression level when glioma grade (grade 2, 3, and 4) increased (P<0.001)." (PMID 40027130, 2025). "Using immunofluorescence, the locations of ATP1B3 and PPP1CA in glioma cells were determined." (PMID 40027130, 2025). "In glioma cells, PPP1CA collaborates with KIF18A to regulate cancer cell proliferation." (PMID 39664902, 2024). "By influencing the MAPK/NF-κB and PPP1CA signaling pathways, ATP1B3 may control the malignant development of gliomas." (PMID 40027130, 2025).
liver cancer (3 papers, 2022 to 2026). An epithelial or non-epithelial malignant neoplasm that arises from the liver. "Notably, CAMK2B showed medium expression in both normal and liver cancer tissues, while CDC20 and PPP1CA were undetected in normal tissue but exhibited medium expression in liver cancer." (PMID 41511815, 2026). "In all three datasets the expression levels of PEA15, PPP1CA and TUFT1 were significantly increased in liver cancer tissue compared to adjacent non-tumorous liver tissue." (PMID 34976171, 2022).
Obesity (3 papers, 2018 to 2024). Accumulation of substantial excess body fat. "These candidates were further refined by searching for genes that have been implicated in NAFLD genome-wide association studies (Ppp1ca), genes associated with other liver disease, (Dguok, Ass1), and obesity-related genes (Slc39a1)." (PMID 29847571, 2018). "The results revealed that 18 of the DMR genes were associated with addiction and obesity (ADCY3; ADCY9; ATF4; CDK5R1; CHRNB2; GABRD; GABRG3; GNB1; GNB3; GRK5; HDAC4; HDAC9; MAP2K1; PDE11A; PDE2A; PDE3A; PPP1CA; SLC6A3)." (PMID 34389046, 2021).
ovarian carcinoma (3 papers, 2011 to 2019). A malignant neoplasm originating from the surface ovarian epithelium. "In subnetwork 8, long-term potentiation was identified as a significant pathway, where PPP1CC and PPP1CA directly interacted with three PCOS-ovarian cancer-shared PCOSrps—i.e., BRCA1, PPP1CC, and URI1—and indirectly interacted with two shared PCOSrps (CDKN1B and SKP2)." (PMID 31216618, 2019).
Alzheimer disease (2 papers, 2022 to 2023). A progressive, neurodegenerative disease characterized by loss of function and death of nerve cells in several areas of the brain leading to loss of cognitive function such as memory and language. "The reduced expression of PPP1CA also contributes to tau hyperphosphorylation, and Alzheimer’s disease brain samples show reduced PPP1CA expression." (PMID 38002279, 2023).
bladder cancer (2 papers, 2010 to 2024). "In bladder cancer, urinary PPP1CA levels can be used to detect tumour recurrence." (PMID 39550701, 2024). "We could use the urinary content of hTERT, SENP1, PPP1CA, and MCM5 to detect bladder cancer recurrence." (PMID 21106093, 2010).
breast tumor (2 papers, 2007). "The amplification and co-amplification with other chromosomes of 11q13 region of chromosome 11 is relatively frequent in breast tumors and overexpression of CCND1 (cyclin D1) and PPP1CA is also seen." (PMID 17883861, 2007).
gastric cancer (2 papers, 2015 to 2020). A primary or metastatic malignant neoplasm involving the stomach. "Another demonstrated that miR-125b targeted the PPP1CA-Rb signal pathway to enhance the migration and invasion of gastric carcinoma cells." (PMID 33224315, 2020). "However, a recent study found that miR-125b promotes cell migration and invasion by targeting the PPP1CA-Rb signal pathway in gastric cancer, resulting in a poor prognosis, which means that miR-125b could be regarded as oncogene in gastric cancer." (PMID 26504803, 2015).